POSTN (periostin)
Diseases named in the same sentence as POSTN in open-access papers (continued):
Sharing a sentence is not in itself a finding about the gene and the disease.
tumor (continued). "Within this structure, POSTN+ fibroblasts and SPP1+ macrophages form a barrier that shields tumor cells from immune cell attacks." (PMID 39716897, 2024). "Among other multicellular proteins, periostin (POSTN) is a key factor for regulating cellular proliferation, and its expression is strongly correlated with tumor progression." (PMID 38468988, 2024). "The overlap of target gene enriched pathways included cell-substrate junction assembly, ECM-receptor interaction, and osteoblast differentiation, suggesting the combined oncogenic effects of POSTN+ fibroblasts and SPP1+ macrophages on tumor cells." (PMID 38519500, 2024). "In short term survival samples, 2 stroma clusters near the tumor edge expressed high COL1A1 and POSTN consistent with myofibroblast phenotype, while two stroma clusters distal to the tumor edge expressed high COL1A1 and CD36 (peri-vascular)." (PMID 38525245, 2024). "Intriguingly, both POSTN+ and PTGDS + CAFs were detected around the tumor islands, suggesting that these CAFs correspond to the mCAFs in our study as we used COL11A1 and PTGDS to localize them in the tissue." (PMID 39516494, 2024). "Higher levels of periostin instigate angiogenesis, enhance WNT signalling and result in a microenvironment propitious for tumour progression and metastasis." (PMID 38532103, 2024). "Studies demonstrated enhanced tumor growth in cardiac remodeling models including TAC-operated mice, low-dose PE-induced HT mice, and ATF3-transgenic mice also reported increased periostin expression in cardiac tissues." (PMID 38279150, 2024). "Therefore, we analyzed whether POSTN expression influences the tumor immune microenvironment." (PMID 38389400, 2024). "The VEGF and MMPs have been identified as crucial indicators of skin cancer progression, with high concentrations of POSTN and CD163+ TAMs in the tumor stroma of skin malignancies leading to increased production of MMP1 and MMP12 in skin lesions." (PMID 37525217, 2023). "The authors interpret this result as confirmation that the CLOCK-POSTN-TBK1 axis is involved in tumor angiogenesis and point to the need for further investigation into the precise molecular interaction between CLOCK, POSTN and TBK1." (PMID 38275375, 2023). "To validate the spatial localization of POSTN+ CAFs and SPP1+ macrophages in the TME of NSCLC, we performed multiplexed IHC (mIHC) using FFPE tumour samples from fifteen NSCLC patients." (PMID 38115703, 2023). "On one hand, GSCs‐secreted periostin (POSTN) promotes TAM recruitment and supports the tumor‐promoting M2 subtype." (PMID 37576862, 2023). "Because of all these properties, periostin is considered one of the important proteins regulating ECM organization, especially collagen, in the PaCa tumor microenvironment and thereby influences the characteristics of cancer cells." (PMID 36830807, 2023). "Estrogen activity can modulate components of the ECM in the tumor microenvironment, upregulating transcripts of COL1A1, and several matricellular proteins such as TNC, FN1, and POSTN." (PMID 37056757, 2023). "Mechanistically, TFAP2A directly binds to the CD133 promoter to ignite tumor stem-like properties in HCC cells and synergizes with periostin/TGFβ1 positive feedback loop to further boost tumor stemness." (PMID 37291585, 2023). "We calculated the relative proportions of POSTN+ CAFs in the scRNA‐seq data of this study and showed that POSTN+ CAFs were more enriched in advanced tumours (stage II/III/IV) than early‐stage tumours (stage I) (p = .041)." (PMID 38115703, 2023). "Representative staining images showed that signals for periostin (POSTN) and osteopontin (SPP1) had similar spatial distribution surrounding tumour nests." (PMID 38115703, 2023). "Ten signaling pathways only existed in the lymphatic metastases, including CD22, CD45, IL16, SPP1, LIGHT, ANGPTL, GRN, ncWNT, PERIOSTIN, and NEGR, in addition to the classical ncWNT pathways that can promote tumor progression." (PMID 37221625, 2023).
tumor (continued). "In another study, the authors found a relationship between the overexpression of periostin by CAFs and the proliferative activity and migration of HNSCC tumor cells." (PMID 38003931, 2023). "POSTN enhances the motility of VHL+ cells and the dissemination of tumor cells by disrupting the vasculature." (PMID 37069149, 2023). "We found significantly higher concentrations of periostin, VEGF-A, IFN-γ, IL-1 β, IL-17 and TNFα in the tumor samples compared with surgical tissue margins." (PMID 35056404, 2022). "In addition they showed that periostin-deficient CSCs did not form tumor spheres and this effects could be reversed by addition of periostin." (PMID 36224629, 2022). "sc-CAFs-NFs analysis revealed a significant increase in CAFs expression of 3 exiting marker genes (FAP, COL11A1 and POSTN) and 2 newly proposed markers (COL6A3 and MFAP2) in all tumor types we studied." (PMID 36263012, 2022). "ELISA and gene expression analysis identified periostin, fibronectin and CTGF as cardiac- and tumor-secreted factors that are highly abundant in PE-infused mice serum as compared with non-infused mice." (PMID 35406672, 2022). "In an orthotopic mouse model with silenced POSTN expression by PNDA-3, reduced primary tumor growth and distant metastasis were found." (PMID 36077762, 2022). "To determine the effect of DDR2′s modulation of POSTN on tumor cell migration and proliferation, we performed wound healing assays with ES2 tumor cells and CAF conditioned media." (PMID 35884543, 2022). "We found significant correlations between periostin levels in tumor and VEGF-A, IFN-γ, IL-1β, and TNFα concentrations in tumor." (PMID 35056404, 2022). "Levels of periostin, VEGF-A TNFα, IFN-γ, IL-1β and IL-17 were measured using ELISA tests, MVD was assessed on CD34-stained specimens, tumor budding was evaluated on H + E slides, and these data were compared with clinicopathological features of the patients." (PMID 35056404, 2022). "It was shown that periostin enhances angiogenesis and metastasis via activating the Akt/PKB pathway, which protects tumor and endothelial cells against stress-induced cell death." (PMID 36224629, 2022). "POSTN is an ECM moiety and an adhesion molecule and has been found to promote tumour growth and metastasis." (PMID 35508298, 2022). "We found that mesothelial cell clearance and invasion by tumor cells were enhanced three-fold when DDR2 and POSTN-expressing CAFs were present compared to DDR2 and POSTN-depleted CAFs." (PMID 35884543, 2022). "We observed that TRPM7 and POSTN expression is significantly enriched in CAFs (p < 10−15) and to a lower extent in endothelial cells from PAAD tumor samples compared with a normal pancreas from GTEX." (PMID 35883700, 2022). "In a study of 30 NSCLC samples, periostin expression was detected in the cytoplasm of tumor epithelia (periostin tumor) and in the cytoplasm of fibroblasts or extracellular matrix (ECM) (periostin stroma)." (PMID 36224629, 2022). "A significant correlation was found between periostin levels in margin and VEGF-A, IFN-γ IL-1 β, IL-17, and TNFα in tumor and margin specimens." (PMID 35056404, 2022). "We observed significant correlation between margin periostin and VEGF-A, IFN-γ, IL-17 and TNFα in tumor and margin specimens." (PMID 35056404, 2022). "Periostin, identified as a matricellular protein and an ECM protein, plays a central role in non-neoplastic diseases." (PMID 36611844, 2022). "The MVD and budding were assessed using a light microscope Results: We found significantly higher concentrations of periostin, VEGF-A, IFN-γ, IL-1 β, IL-17 and TNFα in the tumor samples compared with surgical tissue margins." (PMID 35056404, 2022). "Remarkably, we found a positive correlation between INHBA expression in tumor cells and the surrounding expression of Activin A-exposure genes (FN1 or POSTN) in CAFs, with preferential expression in tumor areas with High infiltrative morphology." (PMID 35986012, 2022).
tumor (continued). "Our volcano plot and GO analysis showed the significant downregulation of tumor-suppressive genes, such as ANOS1, CDH11, COL4A5, POSTN, PTN, and BEX1 in As- transformed cells, which is considered an early event of carcinogenesis." (PMID 35954277, 2022). "Our data demonstrated that tumor-derived factors, among which VEGF-C likely plays a key role, can activate LEC and induce POSTN deposition by FRC, which in turn further promotes lymphangiogenesis." (PMID 35567669, 2022). "Periostin (POSTN), a secreted matricellular protein, involves in many fundamental biological events such as cell proliferation, tumor angiogenesis and metastasis." (PMID 36550569, 2022). "To determine a functional role of POSTN in promoting RCC growth in vivo, we utilized a subcutaneous xenograft tumor model implanted with POSTN-manipulated A498 and ACHN cells." (PMID 34093819, 2021). "Endothelial cells from different sources were mixed and assigned to four cell types, including immune EDCs (CCL5 and CXCL13), lymphatic EDCs (PDPN and PROX1), tumor EDCs (ACKR1 and POSTN), and vascular EDCs (PLVAP and SLC9A3R2)." (PMID 34697289, 2021). "In our study, the expression of POSTN, TNC, CAV1 and FSCN1 found to be localized predominantly in the cytoplasm of the tumour cells." (PMID 33739025, 2021). "Some Authors have observed an accumulation of periostin-stimulated macrophages in plaque-stage MF that may lead to formation of the tumour lesions, while M2 macrophages may play an important role in maintaining an immunosuppressive tumour microenvironment later." (PMID 34485162, 2021). "When investigating the mRNA expression of COL1A2, POSTN, GREM1, MMP1, and MMP9 in patient material, we found all five genes to be upregulated in HNSCC tumor tissue compared to normal oral tissue." (PMID 34283070, 2021). "The expression of POSTN, TNC, CAV1 and FSCN1 was localized predominantly in the cytoplasm of the tumour cells." (PMID 33739025, 2021). "In a Malanchi report, periostin (POSTN) was identified as a component of the ECM and is expressed by fibroblasts in healthy tissue and by stroma of the primary tumor in the breast." (PMID 33418894, 2021). "Periostin and gremlin showed a weak to moderate staining in tumor cell/CAF spheroids compared to tumor cell spheroids." (PMID 34283070, 2021). "Over the past few years, periostin (POSTN), a gene involved in cell survival and angiogenesis, has emerged as a marker for tumor progression and as a novel therapeutic agent in various types of human cancers." (PMID 34164563, 2021). "EDA-containing FN, together with tenascin C, versican and periostin have also been found in other secondary sites prior to tumor cell arrival, and may be important for recruitment of stromal cells as well as for circulating tumor cells to the pre-metastatic niche." (PMID 32426283, 2020). "MSCs have been also shown to improve tumor progression, after injection to the tumor site, through secretion of several growth factors such as TGF-β, epidermal growth factor receptor, periostin, ANG1, PDGF, insulinlike growth factor, and IL-6." (PMID 32793565, 2020). "First, we found that the expression of POSTN was higher in HCC-LM3 cells, a tumor cell line with strong metastatic potential, compared to SMMC-7721 cells." (PMID 33083453, 2020). "This is in accordance with the observed reduction of the pro-tumorigenic factors IL-6, periostin, LIF and, PGE2 which previously have been shown to promote tumour cell growth." (PMID 33060625, 2020). "Our studies found that up-regulation of GDF15 expression in HUVECs was accompanied by increased expression of POSTN, indicating that GDF15 secreted by tumor cells modulates POSTN levels in the extracellular matrix." (PMID 33193874, 2020). "POSTN can bind TNC, a glycoprotein that promotes the metastatic outgrowth of disseminated tumor cells in the secondary site." (PMID 33371274, 2020).
tumor (continued). "As well as increasing tumor vasculature, VEGF also upregulates expression of the macromolecules tenascin C (TNC) and periostin." (PMID 33178210, 2020). "For example, pancreatic cancer cells stimulate stromal cells to secrete POSTN, which induces tumor desmoplasia and EMT to promote tumor progression." (PMID 33083453, 2020). "POI was significantly correlated with tumour size, stage, 3-year survival, EGFR, HIF-1α, periostin, and MMP-9 (p < 0.05)." (PMID 33123565, 2020). "They observed a correlation of stromal periostin expression with more advanced FIGO stage, suboptimal cytoreduction, tumor recurrence, and survival: patients with high periostin expression in tumor stroma had shorter OS and DFS." (PMID 31936272, 2020). "IL-6, periostin, LIF, and prostaglandin E2 (PGE2), are CAF-derived soluble factors that have been described to play a role in tumour progression." (PMID 33060625, 2020). "Expression for MMP3 (t = 4.884, p < 0.0001), SLC2A1 (t = 3.703, p = 0.0006), DDK3 (t = 3.981, p = 0.0003), POSTN (t = 2.061, p = 0.0455), RBP4 (t = 3.048, p = 0.004) and ASPN (t = 2.733, p = 0.0091) was confirmed to be higher in the tumor tissues." (PMID 32854182, 2020). "POSTN was also found to be involved in the epithelial-mesenchymal transition of ESCC cells and was suggested as a predictive factor for tumor invasion and metastasis." (PMID 31950035, 2019). "Interaction of periostin with integrins αvβ3 and αvβ5 activates PI3K–Akt signaling pathway, resulting in increased tumor cell invasion." (PMID 31137693, 2019). "Immunohistochemistry (IHC) on serial sections from patient surgical samples showed the presence of POSTN, PDPN and MYH11 in spatially distinct areas of the tumour, suggesting expression of these markers by different CAF subpopulations." (PMID 30575030, 2019). "Highly interrelated nodes, such as COL1A1, COL1A2, POSTN, ADAMTS4, and CD34, have been reported to regulate the tumor microenvironment and promote the growth, angiogenesis, and invasion of malignancies." (PMID 31480381, 2019). "POSTN was detected to be significantly upregulated in both FF and FFPE tumor samples in this cohort." (PMID 31495056, 2019). "Intriguingly, periostin facilitates the recruitment of CD163+ M2 macrophages, which potently induces immune tolerance and promotes tumor progression." (PMID 30621220, 2019). "In a multivariate analysis including tumor differentiation, venous invasion, TNM stage, and other parameters, POSTN expression level was identified as an independent prognostic factor." (PMID 29946533, 2018). "Periostin (POSTN), another matricellular proteins are secreted by stromal cells to prime the lung stroma for CSC-supportive niche in response to TGF-β3 secretion by tumour cells." (PMID 29506506, 2018). "Among the top differentially expressed genes between tumor and DTC samples, we found genes involved in metastasis initiation and angiogenesis, for example, MGP, BGN, POSTN and ANGPT2, to be upregulated in tumors." (PMID 28921546, 2018). "Interestingly, POSTN could also be sent to the secondary metastatic sites by exosomes and thereby promote metastasis by conditioning the microenvironment of the target tissue before the arrival of tumor cells." (PMID 29946533, 2018). "Periostin is a driver of the EMT and induces expression of MMP-9, MMP-10, and MMP-13, resulting in the degradation of ECM, believed to be crucial for local tumor spread and/or metastasis via invasion and neovascularization." (PMID 29758011, 2018). "Another meta-analysis approach based on PDAC datasets allowed the identification of a 5 genes classifier signature (TMPRSS4, AHNAK2, POSTN, ECT2, SERPINB5) with 95% sensitivity and 89% specificity in discriminating PDAC from non-tumor samples." (PMID 30236127, 2018).
tumor (continued). "We omitted the analysis of POSTN, the most robust gene in cluster 2, as it has been confirmed recently by immunohistochemical staining to be increased in PDAC compared to non-tumor tissues and correlating with disease progression and poor survival." (PMID 29675033, 2018). "Therefore, we hypothesize that POSTN secreted by peri-tumoral activated HSCs may induce the acquisition of stem cell-like properties in residual HCC cells after incomplete thermal ablation to promote tumor progression." (PMID 28526827, 2017). "Presumably, the epigenetic changes during tumor development and progression prevent the inhibitory effects of GPRC5A overexpression on Cp, LCN2 and POSTN in NSCLC cells." (PMID 28088789, 2017). "Activated PSC secrete Periostin in PDAC and stimulate an auto-activation loop for PSC, promote cancer cells survival under hypoxic conditions; thus create a tumour-supportive microenvironment." (PMID 27288147, 2016). "Therefore, we believe that the conflicting impact of CAF-derived POSTN in tumor progression may be partially due to the different tumor types and the different origins of tumors, and further studies are needed to address if and how podosome formation is associated with motility on periostin." (PMID 26857387, 2016). "Stromal fibroblasts present in invasive human breast carcinomas promote tumor growth through elevated SDF-1/CXCL12 secretion, and lung stromal fibroblast-derived periostin creates a metastatic niche for breast CSCs." (PMID 26980947, 2016). "The objective of this study is to clarify if stromal POSTN expression in tumor tissues is prognostic and/or predictive for CRC and elucidate the mechanisms by which stromal POSTN promoted the aggressiveness and drug-resistance of CRC." (PMID 26556874, 2016). "In addition, we have verified that POSTN derives from stromal cells is more than that from epithelial cells including tumor cells of epithelial origin, and evidence has shown that tumor cells of mesenchymal origin could secrete higher concentration of periostin." (PMID 26857387, 2016). "The induction of stromal niche signals by tumor cells, for example expression of extracellular matrix proteins such as PERIOSTIN (POSTN) in the tumor microenvironment, also contributes to the expansion of the metastatic niches." (PMID 27776343, 2016). "CAFs isolated from EAC have a functional myofibroblastic phenotype, and promote tumour cell invasion in vitro and growth in vivo, signalling to EAC cells via secretion of the ECM protein, periostin." (PMID 25345775, 2015). "Paracrine interaction between CAF-secreted periostin and EAC-expressed integrins results in PI3 kinase–Akt activation and increased tumour cell invasion." (PMID 25345775, 2015). "Verification studies using qRT-PCR, immunoblot and IHC assays confirmed that the expressions of S100A2, POSTN, FN1 and KRT17 were, indeed, significantly increased in tumor tissues." (PMID 25874882, 2015). "Periostin (POSTN), a recently characterised matricellular protein, is frequently dysregulated in various malignant cancers and promotes tumor metastatic growth." (PMID 24009721, 2013). "COL1A1, hyaluronan (HA), versican (VCAN), periostin (POSTN) and matrix metalloproteinase (MMP) 9 are all increased and the magnitude of these responses are related to tumor aggressiveness." (PMID 24213323, 2012). "Periostin is reported to be involved in tumor EMT, extracellular matrix degradation, tumor invasion, and distant metastasis, but the mechanism by which it operates is still unclear." (PMID 23056395, 2012). "The effect of silencing Periostin expression by RNAi on proliferation of LNCap cells was determined by MTT assay and tumor xenografts." (PMID 21714934, 2011). "Additionally, the weak positive Periostin expressed tumor cells could be seen in the tissues of 6 xenografts from the group of down-regulated Periostin LNCap cells which had a significant decrease of the amount of Periostin compared to the other two group." (PMID 21714934, 2011).